LINC00857 (long independently transcribed non-coding RNA 857)
Diseases named in the same sentence as LINC00857 in open-access papers (continued):
Sharing a sentence is not in itself a finding about the gene and the disease.
lung (1 paper, 2016). "To determine if LINC00857 overexpression arises from genomic amplification, we examined potential DNA copy number alterations in 90 lung ADs by Affymetrix SNP6.0 array (unpublished data)." (PMID 26862852, 2016).
LINC00857 also shares sentences with these, for which no sentence is quoted: colon cancer (1 paper); skin cancer (1); small cell lung carcinoma (1).